BNIP3L (BCL2 interacting protein 3 like)
Diseases named in the same sentence as BNIP3L in open-access papers (continued):
Sharing a sentence is not in itself a finding about the gene and the disease.
Hyperglycemia (2 papers, 2020 to 2022). An increased concentration of glucose in the blood. "We detected the decrease of LC3-II/LC3-I ratio accompanied with the increase of P62 and BNIP3L/Nix in hyperglycemia groups (P < 0.05)." (PMID 33424763, 2020). "The accumulated BNIP3L/Nix was detected in renal tubular cells under acute hyperglycemia treatment in this study." (PMID 33424763, 2020). "Consistent with the results in vivo, we also detected the gradually down-regulated LC3-II/LC3-I ratio accompanied with the gradually up-regulated P62 and BNIP3L/Nix in hyperglycemia groups (P < 0.05)." (PMID 33424763, 2020). "ROS was activated, mitochondrial membrane potential and LC3-II/LC3-I ratio were decreased but P62 and BNIP3L/Nix were increased in hyperglycemia groups (P < 0.05), which were reversed by AMPK activation or mTOR inhibition." (PMID 33424763, 2020).
mitochondrial DNA depletion syndrome 13 (2 papers, 2024 to 2025). Any mitochondrial DNA depletion syndrome in which the cause of the disease is a mutation in the FBXL4 gene. "The post-translational regulation of BNIP3L and BNIP3 is disrupted in mitochondrial DNA depletion syndrome 13 (MTDPS13), a multi-systemic disorder caused by mutations in the FBXL4 gene and characterized by elevated mitophagy and mitochondrial DNA/mtDNA depletion in patient fibroblasts." (PMID 38423516, 2024). "The post-translational regulation of BNIP3L and BNIP3 is disrupted in mitochondrial DNA depletion syndrome 13 (MTDPS13), a multisystem disorder disease caused by variations in the FBXL4 gene." (PMID 40352787, 2025).
myocardial infarction (2 papers, 2022). Gross necrosis of the myocardium, as a result of interruption of the blood supply to the area, as in coronary thrombosis. "We focused on cardiac mitophagy during and following myocardial infarction by highlighting the role and the regulation of PI NK1/parkin-; FUNDC1-; BNIP3- and BNIP3L/NIX-induced mitophagy during ischemia and reperfusion." (PMID 35053316, 2022).
ovarian tumors (2 papers, 2003 to 2015). "Genetic analysis of BNIP3L in 40 primary ovarian and 25 primary breast tumours identified one somatic, intronic mutation in one ovarian tumour, as well as several polymorphisms, including one resulting in an amino-acid substitution." (PMID 12610513, 2003). "LOH analysis was carried out on 40 primary ovarian tumours and 25 primary breast tumours, and their corresponding constitutional DNA to assess allelic loss at the BNIP3L locus." (PMID 12610513, 2003). "Mutation analysis of BNIP3L was carried out on the same series of 40 primary ovarian tumours and 25 primary breast tumours by DHPLC." (PMID 12610513, 2003).
pancreatic ductal adenocarcinoma (2 papers, 2021 to 2023). An infiltrating adenocarcinoma that arises from the epithelial cells of the pancreas. "The level of BNIP3L is high in organoids derived from murine pancreatic intraepithelial neoplasia, thereby delaying progression of pancreatic ductal adenocarcinoma (PDAC) and suggests BNIP3L-mediated mitophagy promotes tumorigenesis." (PMID 34930907, 2021).
autoimmune disease (1 paper, 2024). A disorder resulting from loss of function or tissue destruction of an organ or multiple organs, arising from humoral or cellular immune responses of the individual to their own tissue constituents. "Numerous studies showed that BNIP3L/NIX was capable of protecting cells from damaged mitochondria through inducing mitophagy in kinds of disease, including ischemic brains, lipotoxicity, synapse defects, cancers, and immunity and autoimmune diseases." (PMID 38326905, 2024).
cognitive decline (1 paper, 2025). "To investigate whether changes in mitophagy reflect cognitive decline in FTLD individuals, we correlated the levels of mitophagy biomarkers (PINK1, ULK1, BNIP3L, TFEB) with global cognition (MMSE) and cognitive composite scores." (PMID 39972393, 2025).
colitis (1 paper, 2025). Inflammation of the colon. "Supporting this, Nix−/− mice, which lack the mitophagy receptor Nix/Bnip3l, are more susceptible to DSS-induced colitis and show greater mitochondrial damage in colonic epithelial cells." (PMID 39943187, 2025).
cytomegalovirus infection (1 paper, 2020). A herpesvirus infection caused by Cytomegalovirus. "Lower expression of BCL2 Interacting Protein 3 like (BNIP3L) gene was experienced in SARS-CoV infection, while downregulation of this gene was associated with a reduction of NK cell memory and their response to cytomegalovirus infection." (PMID 32754004, 2020).
Ewing sarcoma (1 paper, 2024). A small round cell tumor that lacks morphologic, immunohistochemical, and electron microscopic evidence of neuroectodermal differentiation. "Ultimately, another study has demonstrated that the endogenous degradation of BNIP3L confers survival to Ewing’s sarcoma cells." (PMID 39524226, 2024).
fibrosis (1 paper, 2019). the formation of excess fibrous connective tissue in an organ or tissue in a reparative or reactive process. "We validated the up‐regulation of UBE2V1, BNIP3L mRNAs, RP11‐128N14.5 lncRNA, TGFB2/TGFB2‐OT1 coding/lncRNA in patients with NAS ≥ 5 (vs NAS ≤ 4) and the up‐regulation of HBA2 mRNA, TGFB2/TGFB2‐OT1 coding/lncRNA in patients with Fibrosis stages = 3‐4 (vs F = 0‐2)." (PMID 31169972, 2019).
Hypertension (1 paper, 2017). The presence of chronic increased pressure in the systemic arterial system. "Additionally, in vivo, the inhibition of BNIP3L expression with DOX or MET attenuated AAC-induced ECM protein expression and collagen production, which further indicates that BNIP3L has pro-fibrotic activities during hypertension." (PMID 28507335, 2017).
hypertensive heart disease (1 paper, 2017). Abnormal enlargement of the heart resulting from long-standing hypertension. "To a better understanding of the function of BNIP3L in hypertensive heart disease, we detected the cellular distribution of BNIP3L in the heart sections by immunohistochemistry." (PMID 28507335, 2017). "First, we explored the cellular distribution of BNIP3L in the heart tissue, contributing to a deeper understanding for its function in hypertensive heart disease." (PMID 28507335, 2017).
hyperthyroidism (1 paper, 2022). Overactivity of the thyroid gland resulting in overproduction of thyroid hormone and increased metabolic rate. "In the state of hyperthyroidism, the amount of BNIP3L in HR did not change." (PMID 36430802, 2022).
hypertrophic cardiomyopathy (1 paper, 2025). A condition in which the myocardium is hypertrophied without an obvious cause. "In hypertrophic cardiomyopathy, hypoxia-independent induction of BNIP3L promotes cardiomyocyte death and drives the transition toward acquired DCM." (PMID 40034852, 2025).
injury (1 paper, 2021). Damage inflicted on the body as the direct or indirect result of an external force, with or without disruption of structural continuity. "In the case of acute brain injury, BNIP3L protects the brain from damage." (PMID 34930907, 2021).
iron deficiency (1 paper, 2018). "Lastly, we report differences in the expression pattern of markers for BNIP3 and BNIP3L-mediated mitophagy in COPD patients suffering from either iron deficiency or systemic inflammation." (PMID 30302028, 2018). "In conclusion, iron deficiency results in differential expression of BNIP3 and BNIP3L-related mitophagy markers, but does not seem to result in increased overall mitophagy in ID-COPD in our study population." (PMID 30302028, 2018).
kidney clear cell carcinoma (1 paper, 2025). "The expression of BNIP3L was high in kidney clear cell carcinoma (KIRC), but low in BRCA and chromophobe kidney cancer (KICH)." (PMID 39859167, 2025).
MELAS (1 paper, 2024). "It is worth noting that the levels of PINK1 and BNIP3L were decreased in the muscle of m.3243 A > G MELAS patients compared with the control group, indicating inhibition of mitochondrial autophagy initiation in MELAS." (PMID 38741129, 2024).
metastatic tumors (1 paper, 2025). "In metastatic tumors, pathway and TF analyses revealed strong hypoxia-inducible factor-1α–driven hypoxia activation, influencing glycolysis (SLC2A1, SLC2A3, PGK1, PDK1, PGM1, and ALDOA), angiogenesis (ANGPTL4 and ADM), and survival in low oxygen (BNIP3, BNIP3L, and NDRG1)." (PMID 40736012, 2025).
Obesity (1 paper, 2025). Accumulation of substantial excess body fat. "Our study demonstrated that the mitophagy-related markers PINK1, PARK2, and BNIP3L were significantly upregulated in the visceral adipose tissue of individuals with obesity." (PMID 41334630, 2025). "Our findings reinforce these observations, suggesting that the PINK1/Parkin axis is upregulated as a compensatory mechanism in human obesity and BNIP3L protein expression is increased in adipocytes." (PMID 41334630, 2025). "To summarize, our study demonstrates a significant upregulation of mitophagy-related markers, including PINK1, PARK2, and BNIP3L, in the adipocytes of visceral adipose tissue in individuals with obesity." (PMID 41334630, 2025). "In human obesity, adipose tissue expansion and localized hypoxia may amplify the role of BNIP3L in hypoxia-induced mitophagy, driving mitochondrial turnover while inadvertently sustaining inflammatory signalling via DAMPs (e.g. mtDNA) and inflammation." (PMID 41334630, 2025). "A modest upregulation of BNIP3L levels were found during obesity in animal studies This might reflect tissue and species-specific differences in the regulation of mitophagy pathways." (PMID 41334630, 2025). "Moreover, the expression of PARK2, PINK1, and BNIP3L was significantly upregulated in the obesity group, suggesting increased mitophagy activity in adipose tissue." (PMID 41334630, 2025). "In parallel, exploring the therapeutic potential of modulating mitophagy pathways, for example, by using pharmacological agents to activate or inhibit BNIP3L, may help determine whether targeting mitophagy can effectively reduce adipose tissue inflammation and improve metabolic outcomes in obesity." (PMID 41334630, 2025). "Comprehending the interplay between mitophagy, inflammation, and metabolic health in obesity requires functional studies, such as targeted knockdown of PINK1, PARK2, or BNIP3L in adipocytes, to elucidate their specific roles in regulating mitochondrial quality and inflammatory responses." (PMID 41334630, 2025).
oncocytoma (1 paper, 2008). "Therefore, we propose that the downregulation of BNIP3L is the result of chromosome-pairing induced upregulation of EGLN2 and that downregulation of BNIP3L contributes to the inhibition of apoptosis to facilitate oncocytoma cell survival and growth." (PMID 18773095, 2008).
osteonecrosis (1 paper, 2023). A none disease characterized by death of bone tissue due to a lack of blood supply. "This shows that NIX associated with BNIP3L can cause erythropenia under hypoxic conditions, which coincides with the ischemia and hypoxia that cause osteonecrosis of the femoral head." (PMID 36631868, 2023). "Together, these data suggested that the four key differential genes ASXL1, BNIP3L, FCGR2A and TYROBP were significantly associated with osteonecrosis of the femoral head." (PMID 36631868, 2023). "The results showed that eighteen differential genes were annotated, among which BNIP3L, ASXL1, FCGR2A and TYROBP were highly correlated with osteonecrosis." (PMID 36631868, 2023). "Through animal experiments, it was confirmed that ASXL1, BNIP3L, FCGR2A and TYROBP screened from the comparative analysis of multiple genes in the database were closely related to GIONFH, which is important for early diagnosis of Glucocorticoid-induced osteonecrosis of the femoral head." (PMID 36631868, 2023). "By consulting the literature, we could not find that the BNIP3L and ASXL1 were directly related to the occurrence of osteonecrosis." (PMID 36631868, 2023).
ovarian serous cystadenocarcinoma (1 paper, 2025). A malignant serous cystic epithelial neoplasm arising from the ovary. "Homozygous deletions were most prominent in BNIP3L, especially in prostate adenocarcinoma (PRAD), rectal adenocarcinoma (READ) and ovarian serous cystadenocarcinoma (OV)." (PMID 39859167, 2025).
periodontitis (1 paper, 2025). An acute or chronic inflammatory process that affects the tissues that surround and support the teeth. "BNIP3L and CTTN were downregulated in periodontitis, correlating negatively with disease prevalence, immune infiltration, and inflammatory pathways, whereas VPS13C and MAP1LC3B were upregulated, showing positive correlations." (PMID 40859550, 2025).
prostate adenocarcinoma (1 paper, 2025). "In prostate adenocarcinoma (PRAD), OPTN, PRKN, BNIP3L, PINK1, and MAP1LC3A were significantly downregulated." (PMID 39859167, 2025).
pulmonary disease (1 paper, 2020). "In fact, increased expression of BNIP3L points towards aggravated mitophagy, which is a hallmark of pulmonary disease conditions including COPD and IPF." (PMID 33290406, 2020).
renal oncocytoma (1 paper, 2008). "In addition, the recently identified tumor suppressor BNIP3L is downregulated three-fold in the renal oncocytoma cells." (PMID 18773095, 2008). "Overexpression of ELGN2 in renal oncocytoma increased ubiquitin-mediated destruction of HIF and concomitantly suppressed the expression of several HIF-target genes, including the pro-death BNIP3L gene." (PMID 18773095, 2008).
sarcoma (1 paper, 2022). A usually aggressive malignant neoplasm of the soft tissue or bone. "The sarcoma and LUAD signatures had three common genes (PPFIA4, BNIP3L, NDRG1)." (PMID 35079065, 2022).
steatosis (1 paper, 2019). Increased lipid within the cytoplasm of cells. "The up‐regulation of UBE2V1, RP11‐128N14.5, BNIP3L and TGFB2/TGFB2‐OT1 in NAS ≥ 5 vs NAS ≤ 4 patients, RP11‐128N14.5 in NASH vs simple steatosis and the up‐regulation of HBA2, and TGFB2/TGFB2‐OT1 in F = 3‐4 vs F = 0‐2 patients were also confirmed in the external validation cohort." (PMID 31169972, 2019).
subarachnoid hemorrhage (1 paper, 2025). A serious neurological disorder characterized by intracranial hemorrhage into the subarachnoid space. "Supporting this mechanism, clinical cerebrospinal fluid (CSF) samples from patients with subarachnoid hemorrhage have shown upregulation of BNIP3L/NIX during ischemic stress." (PMID 41007413, 2025).
tumor (55 papers, 2003 to 2026). "The other candidate gene, BCL2 interacting protein 3 like (BNIP3L) which was crucial for hypoxia-induced mitophagy and tumor progression, had two convergent missense mutations with the Py. ru. but only one with On. ta." (PMID 33370292, 2020). "As a mitochondrial outer membrane protein, NIX/BNIP3L can both mediate apoptosis to inhibit tumor cell growth and promote tumor cell survival by clearing intracellular reactive oxygen species (ROS) through mitophagy." (PMID 41744611, 2026). "The gene BNIP3L at 8p21.2 has been suggested to have a tumor suppressive effect in various cancer types." (PMID 40564925, 2025). "Under extreme stimulation, it can form a complex with BNIP3L to induce excessive autophagic degradation in tumor cells." (PMID 40761374, 2025). "Compared to those in normal tissues, APOE, STEAP4, and C1QTNF3 expressions were upregulated in tumor tissues, whereas BNIP3L and PPARGC1A expressions were downregulated." (PMID 39524226, 2024). "BNIP3L is recognized as a tumor suppressor gene and a link between BNIP3L-related autophagy/mitophagy activity and cancer cell death has recently been investigated." (PMID 34930907, 2021). "The RNA oncomir gene mir-30d promotes tumor progression and impaired the expression of autophagy genes including Bnip3l." (PMID 34930907, 2021). "Both Bnip3 and Bnip3l were transcriptionally upregulated in CHO-K1 cells subjected to hypoxic conditions, but Bnip3l showed a considerably lower sensitivity to hypoxia, which was also observed in several tumor cell lines." (PMID 34930907, 2021). "The authors showed that miR-30a has binding sites in the 3′UTRs of the tumour suppressor genes BNIP3L, PRDM9, and SEPT7, and that these target genes were upregulated following knockdown of miR-30a-5p." (PMID 34074015, 2021). "It is also a challenge to distinguish the mitophagy-dependent and -independent role of BNIP3L in tumor biology." (PMID 33262988, 2020). "Consistent with their ability to induce cell death, BNIP3 and BNIP3L inhibit tumor growth especially in hypoxia conditions." (PMID 26432836, 2015). "The tumor suppressor genes BNIP3L, PRDM9, and SEPT7 were each found to have direct 3’UTR binding sites with miR-30a-5p." (PMID 26472042, 2015). "In the case of a possible tumor suppressor, BNIP3L, the combination of TFs FOS and PU1 binding to the gene’s promoter (as observed in GM12878 cells) predicted the gene’s expression accurately only in B-cells." (PMID 22721266, 2012). "Previous reports implied that Bnip3L/Nix play important roles in hypoxia-dependent cell death and act as tumor suppressors." (PMID 22984526, 2012). "In this regard, further studies must be performed to check BNIP3 and BNIP3L status in the different tumour tissues." (PMID 20461082, 2010). "The results of the staining revealed the highest staining score of 3 for BNIP3l in the primary tumour." (PMID 17940512, 2007). "Results provided here suggested that LBX2-AS1 positively regulated the FOXO3A expression while negatively affected the BNIP3L level, and that knockdown of LBX2-AS1 apparently upregulated the mitophagy level through BNIP3L which finally suppressed the tumor progression." (PMID 38326905, 2024). "BNIP3L is a Bcl-2 family protein that is essential for both apoptosis and mitophagy, the latter being a process that degrades mitochondria and can potentially limit tumor growth." (PMID 39524226, 2024). "Furthermore, the oncogenic microRNA mir-30d facilitates tumor progression and adversely affects the expression of autophagy-related genes, including BNIP3L." (PMID 39524226, 2024).